SH2D6 (SH2 domain containing 6)
Synonyms: FLJ35993; SLNK
Tractability: No criterion of Open Targets' tractability assessment is met for any kind of drug.
Gene: Protein-coding gene on chromosome 2 (85,418,714 to 85,437,029, forward strand). Ensembl gene ENSG00000152292.
Gene Ontology:
Molecular function: protein-macromolecule adaptor activity
Biological process: cell surface receptor protein tyrosine kinase signaling pathway; intracellular signal transduction
Cellular component: cytoplasm
Genetic constraint (gnomAD): Loss-of-function variants: 29 observed, 27.17 expected, observed/expected ratio (o/e) 1.07, 90% interval 0.79 to 1.46. The upper end of that interval is the gene's LOEUF score, 1.46, which puts it in group 6 of 6, group 1 being the genes least tolerant of losing a copy. Missense variants: 233 observed, 263.83 expected, observed/expected ratio (o/e) 0.88, 90% interval 0.79 to 0.98. Synonymous variants: 91 observed, 102.96 expected, observed/expected ratio (o/e) 0.88, 90% interval 0.75 to 1.05.
Homologues: Orthologues: macaque SH2D6 (73% identical), rat Sh2d6 (69% identical), mouse Sh2d6 (67% identical), dog SH2D6 (52% identical), chimpanzee SH2D6 (41% identical), tropical clawed frog sh2d6 (28% identical). Paralogues in human: BLNK (27% identical), LCP2 (22% identical), CLNK (20% identical).
Diseases named in the same sentence as SH2D6 in open-access papers:
SH2D6 is named in the same sentence as 7 diseases in open-access papers, as found by Europe PMC text mining. Sharing a sentence is not in itself a finding about the gene and the disease. The quoted sentences say what the papers report.
autism spectrum disorder (3 papers, 2020 to 2023). A spectrum of developmental disorders that includes autism, and Asperger syndrome. "A copy number variation analysis suggests that microdeletion of SH2D6 may be responsible for the generation of chimeric transcripts by ELMOD3 and SH2D6 fusions, which may be involved in autism spectrum disorder (ASD) phenotypes along with other variants." (PMID 37554505, 2023).
acne (1 paper, 2023). An inflammatory process of the sebaceous glands which is characterized by comedones, nodules, papules and/or pustules on the skin. "We found that four CpG loci mediated the genetic risk of severe acne, three of which, cg03020863, cg20652636, and cg19964325, were located on the PDGFD gene body, the SH2D6 intron variant, and the 5’ UTR of the IL1R1 gene, respectively." (PMID 37554505, 2023).
adenoma (1 paper, 2022). A neoplasm arising from the epithelium. "Nine and fourteen of 20 patients had adenoma precursor cell population with high BMX and SH2D6 levels, respectively." (PMID 35221332, 2022).
Hearing impairment (1 paper, 2019). A decreased magnitude of the sensory perception of sound. "Recently, a homozygous deletion affecting the last three exons of ELMOD3, the entire CAPG gene, and the first non-coding exon of SH2D6 has been identified in a Tunisian ASD proband with ID and hearing impairment." (PMID 30736458, 2019).
SH2D6 also shares sentences with these, for which no sentence is quoted: autism (1 paper); colon cancer (1); Rett syndrome (1).